TLR4 (toll like receptor 4)
Diseases named in the same sentence as TLR4 in open-access papers (continued):
Sharing a sentence is not in itself a finding about the gene and the disease.
cancer (continued). "Meanwhile, miRNAs also interacted with some other conserved signalling pathways, such as TLR4, Wnt//β‐catenin and phosphatidylinositol 3‐Kinase/Protein Kinase B, to influence cancer cell proliferation, metastasis or maintenance of cancer cell stemness." (PMID 37138536, 2023). "TLR4 promotes cancer progression by activating several signaling pathways, but in this particular study, M2 macrophages specifically activated the STAT3 signaling pathway." (PMID 37896221, 2023). "Cancer eradication requires HMGB1 to bind to Toll-like receptor 4, activating immune cells through signaling pathways." (PMID 37291495, 2023). "To further verify our analysis, we selected TLR4 as the representative of ICDRGs and evaluated its expression on the lung normal cells and cancer cells in vitro." (PMID 37553698, 2023). "Initially, we thought that S100A8 mainly plays a role in premetastatic niche formation, but it has been reported that various types of cancer cells also express TLR4 at the cell surface." (PMID 36932197, 2023). "For instance, lipopolysaccharide (LPS), a component of the Gram-negative bacterial cell wall, which is recognised by Toll-like Receptor 4 (TLR4), is one of the molecules derived from gut bacteria that has been demonstrated to promote cancer." (PMID 36902427, 2023). "Mechanistically, HNRNPA2B1 can enhance this process by enriching at the m6A sites of TLR4, thus facilitating cancer progression." (PMID 37055798, 2023). "IL-6, IL-17, TNF-α, TLR-2, and TLR-4 were significantly more highly expressed in the cancer tissues (p < 0.05)." (PMID 38075864, 2023). "eNAMPT is involved in modulating the cancer microenvironment by enhancing its metabolism, activates the pro-inflammatory NF-κB pathway by binding to the Toll-like receptor 4 (TLR4)." (PMID 37175631, 2023). "Monophosphoryl lipid A, a TLR-4 agonist, has been evaluated as an adjuvant for anti-cancer vaccines in people, and an in vitro study showed it can activate canine macrophages as well." (PMID 37090720, 2023). "Previous studies revealed that TLR4 signaling is closely related to inflammation and cancer progression." (PMID 37576399, 2023). "MiR-182 is directly suppressive of TLR4, which leads to NF-κB inactivation and M2 polarization of TAMs; this mechanism is triggered by cancer cells inducing miR-182 expression in macrophages through TGF-β signaling." (PMID 37211559, 2023). "Here, we reveal how TNC produced by cancer cells initiates activation of macrophages via TLR4 leading to induction of vascular niches." (PMID 35469015, 2022). "While the majority of 33 forms of cancer exhibit decreased TLR4 expression in comparison to normal tissues, only a few cancers (such as GBM, KIRC, and STAD) exhibit the opposite trend." (PMID 35801728, 2022). "The addition of TLR4 inhibitor markedly reduced LPS-induced production of TNFα by the cancer cells, suggesting that LPS-induced TNFα production by the cancer cells is TLR4 dependent." (PMID 36119107, 2022). "TLR3 and TLR10 were found to be significant in nine malignancies, while TLR4 was shown to be significant in eight cancers." (PMID 35801728, 2022). "This study aimed to investigate the relationship between PAUF and TLR4 expressed on PC cells and their effects on cancer mobility." (PMID 36232715, 2022). "In cancer colonocytes, the expression of TLR4 and IL1R increased after BM + hPA120 treatment, whereas the secretion of IL-8 and MYD88 and TNFR expression decreased (p < 0.01)." (PMID 36296918, 2022). "When exposed to severe hypoxia, necrotic cancer cell debris can stimulate IL-1β secretion in macrophages via TLR4/TRIF/NF-κB signaling." (PMID 36071472, 2022). "Initially, we thought that S100A8 would mainly play a role in premetastatic niche formation, but it has been reported that various types of cancer cells also by themselves express TLR4 at the cell surface." (PMID 35780158, 2022).
cancer (continued). "So far, it has been recognized that 67LR mediates many functions of EGCG, such as the anti-cancer effect and toll-like receptor 4 (TLR4) signaling inhibition." (PMID 36296376, 2022). "Despite their great potential in vaccines, TLR4 agonists have been confined in their efficacy as monotherapies against cancer." (PMID 35745800, 2022). "To investigate the potential binding of PAUF with TLR4 on the plasma membrane of the cancer cells, we used a chemical crosslinker BS3, which is a membrane-impermeable agent that possesses a spacer arm of 1.14 nm." (PMID 36232715, 2022). "Regarding the TRAF6-BECN1 signaling axis for cancer progression in response to TLR4 stimulation (depicted in the left), TRAF6 can interact with BECN1 and induce ubiquitination of BECN1, leading to the induction of autophagy (indicated as a black arrow)." (PMID 35422093, 2022). "Following cancer-induced activation of Toll-like receptor 4 in skeletal muscle, p38β MAPK phosphorylates Ser-12 on p300 to stimulate C/EBPβ acetylation." (PMID 36091226, 2022). "As mentioned in the Introduction, the S100 soil sensor receptors (SSSRs) in cancer cells include the classical receptors TLR4 and RAGE." (PMID 36142212, 2022). "For example, vaginal isolated Lactococcus lactis can decrease TLR-4, miR-21, and miR-200b expression, among which the miRNA-21 and miR-200 family were found to be connected with cancer metastasis, and overall survival rate in ovarian cancer." (PMID 36360311, 2022). "In cancer colonocytes, the activation of pro-inflammatory genes was not so evident compared to the healthy ones, but elevated levels of TLR4, IL1R1 and TNFα in some bacteria- and bacteria with hPA120-treated HCT116 cells were found." (PMID 36296918, 2022). "Recent studies have demonstrated that interruption of TRAF6-BECN1 signaling induced by TLR4 can lead to inhibition of autophagy induction, resulting in attenuated cancer migration and invasion." (PMID 35422093, 2022). "Meanwhile, the rank of TLR4 mRNA expression levels in the six PC cell lines from the current study was compared to that of the Cancer Cell Line Encyclopedia (CCLE)." (PMID 36232715, 2022). "ERK phosphorylation and TLR4 activation have been reported to play crucial roles in modulating drug resistance in cancer cells by contributing to the anti-apoptosis effect and promoting cell survival." (PMID 35890097, 2022). "In spontaneous models of tumorigenesis, mice with Col6a1+ fibroblast-specific deletions of Tlr4, Myd88, or Ptgs2 (encodes an enzyme important for PGE2 production) exhibit reduced cancer development." (PMID 36591258, 2022). "Based on these results, induction and/or amplification of the TLR4 signaling pathway was suggested as a potential treatment strategy in specific cancers." (PMID 36678520, 2022). "Further experiments showed that radiation therapy promotes NET production via cancer-derived HMGB1 interacting with TLR4 on neutrophils, and the inhibition of HMGB1 or NETs showed good results in resolving radiation therapy resistance." (PMID 36555469, 2022). "TLR4 activation increases the cellular generation of ROS, which stimulates cancer-induced muscle wasting." (PMID 36078164, 2022). "In contrast, co-treatment of these cells with LPS and autophagy inhibitors such as 3-MA and CQ attenuated cancer migration and invasion induced by TLR4 stimulation." (PMID 35422093, 2022). "On the other side, cancer colonocytes activated the expression of proinflammatory TLR4 and IL1R1 receptors, while reducing MYD88 in cells treated with the mixture of bacteria and hPA120." (PMID 36296918, 2022). "Along the paclitaxel-mediated ICD, the cancer cell autonomous TLR4 signaling is essential to the release of DAMPs, which led, in an autocrine manner, to the activation of the NF-κB-mediated CCL2 transcription, together with CXCL10." (PMID 36429101, 2022).
cancer (continued). "It was found that inhibition of Toll-like receptor 4 (TLR4) induced OC cell cycle arrest and apoptosis and prevented the proliferation of cancer cells." (PMID 35911695, 2022). "This bacterium upregulates miR-21 in cancer by activating the tlr4-myd88 signaling pathway, decreasing protein levels of tumor suppressor genes RASA1 and PDCD4, thereby promoting CRC growth." (PMID 36360311, 2022). "It is well known that LPS binds TLR4 to recruit downstream signaling and/or adapter molecules, leading to gene expression related to cancer cell proliferation, survival, invasion, and metastasis." (PMID 36119107, 2022). "Initially, we thought that S100A8 mainly would play a role in premetastatic niche formation, but it has been reported that various types of cancer cells also by themselves express TLR4 at the cell surface." (PMID 35780158, 2022). "Taken together, our data demonstrated that TLR4-expressing macrophages played a key role in promoting cancer progression." (PMID 36542153, 2022). "TLR4 expression on CD103+ DC-like cells, for example, can boost CD8 + T cell infiltration in malignancies, making previously unresponsive cancers susceptible to checkpoint blockade therapy." (PMID 35801728, 2022). "The apoptosis caused by LPS plus SM-164 is blocked by toll-like receptor 4 (TLR4) or MyD88 inhibitor, which inhibits LPS-induced TNFα production by the cancer cells." (PMID 36119107, 2022). "To further define the role of TLR4+/+ macrophages in cancer development, we then isolated and characterized the intratumoral macrophages, typically defined as CD45+Ly6G−CD11b+F4/80+CD3−." (PMID 36542153, 2022). "Taken together, the cancer-promoting transcription factor Otc4A activates the NF-κB signaling pathway by reducing the regulatory effect of miR-7-5p on TLR4 level and then enhancing the proliferation, invasion, and cell stemness of CRC cells HT29." (PMID 36199554, 2022). "In cancer cells such as lung, liver, gastric, pancreatic, ovarian, and colon cancer, TLR4 expression is elevated." (PMID 35955552, 2022). "Other possible signaling mechanisms include the downregulation of Wnt/β-catenin, pAkt and ERK1/2 pathways and inhibition of TLR4 (Toll-like receptor 4), all of which play significant roles in cancer cell proliferation and metastasis." (PMID 35399074, 2022). "TLR4 agonist has strong immune effects on tumors and can be applied as an adjuvant in the treatment of cancer." (PMID 35090304, 2022). "TLR4-positive cells increased from normal samples to the surrounding epithelium and further increased in cancer samples, suggesting an important role of TLR4 in carcinogenesis." (PMID 35327577, 2022). "Cold-inducible RNA-binding protein (CIRP), which is released by cold stimuli, and serum amyloid A (SAA), which is involved in TLR4-mediated cancer metastasis, also trigger TLR4 activation." (PMID 35712350, 2022). "Human PLC5 cancer cells with low TLR4 expression were cultured in the presence of LPS (10 ng/mL) to mimic chronic inflammatory response." (PMID 35955552, 2022). "Our results indicated NOTCH1, NOTCH3, FLCN, SOD1, SOD2, NF1, and TLR4 as upregulated proteins in different cancer types highlighting their role in cancer progression." (PMID 35001007, 2022). "Cancer migration/invasion-promoting effects mediated by TLR4 pathways were observed on molecular levels (such as E-cadherin and MMP9) in multiple studies, for study simplicity, we did not evaluate migration-related molecular changes in this study." (PMID 36232715, 2022). "Compared with other molecules in the TLR family, TLR4 is relatively highly expressed at the transcriptome level in pan-cancer studies, close behind TLR2." (PMID 35801728, 2022).
cancer (continued). "To find out if endogenous substances including PAUF can exert a cancer migration-promoting effect via TLR4, we conducted a migration study in PC cell lines with low to high level of TLR4 activity, without adding any migration-promoting treatment." (PMID 36232715, 2022). "Meanwhile, the gut microbiota mixes from miR-148a–/– mice, instead of WT mice, promoted cancer cell growth dependent on TLR4." (PMID 34914638, 2022). "TLR4 and pSTAT3 are key players in cancer inflammation and immune evasion; however, their role in the peripheral blood (PB) is largely unexplored." (PMID 35205801, 2022). "As TLR4 expression increases, cancer cells become more sensitive to medicines such as megestrol acetate, isotretinoin, entinostat, and okadaic acid." (PMID 35801728, 2022). "Of note, cathepsin-mediated TLR cleavage and activation is also essential for dendritic cell function as another significant cellular contributor to TME, based on TLR-4 expression synergizing with cancer cell progression by it positively regulating EMT." (PMID 34918208, 2022). "Recently, a direct effect of Toll-Like Receptor-4 (TLR4) disruption on adipose tissue remodeling and cancer cachexia was reported." (PMID 35646636, 2022). "LPS and the other two potent TLR4 agonists have been proven to be effective in treating a variety of carcinomas." (PMID 35884586, 2022). "In TLR4-positive cancer cells, HMGB1 triggers the formation of an autocrine loop which induces galectin-9 expression." (PMID 34234778, 2021). "Here we report for the first time that the role of HMGB1 in anti-cancer immune evasion is determined by the TLR4." (PMID 34234778, 2021). "On the other hand, it has also been documented that TLR4 activation on immune cells is protective in the context of cancer and is necessary for the efficacy of chemotherapy or radiotherapy." (PMID 34771442, 2021). "Through the Genotype-Tissue Expression (GTEx) and The Cancer Genome Atlas (TCGA) databases, the distinct expression of the TLR4 gene in 24 tumors and normal tissues was analyzed." (PMID 34631699, 2021). "TLR4 plays a major role in mediating cancer-induced activation of p38β MAPK, NF-κB and AKT in skeletal muscle cells." (PMID 34950660, 2021). "In brief, TLR4 is a major player of the innate immune response and is expressed by immune cells of the tumour microenvironment as well as cancer cells." (PMID 35004315, 2021). "From these interactions, the net effect of opioids acting on TLR4 on the course of cancer cannot be predicted." (PMID 35004315, 2021). "Recently, it was shown that Paclitaxel (a cytostatic drug used in cancer treatment) also acts via TLR-4 to reprogram TAMs toward M1 phenotype." (PMID 33919517, 2021). "Our study has identified a critical regulator of CRC growth under HFD conditions, and provides evidence to support the development of TLR4-targeting therapeutics for cancer treatment." (PMID 34385421, 2021). "The unique response of these cancer cells to bacterial antigen was dampened significantly in the presence of a Toll-like receptor 4 inhibitor peptide." (PMID 34771464, 2021). "Univariate Cox proportional hazards regression analysis was used to identify the cancer types whose TLR4 gene expression was related to prognosis." (PMID 34631699, 2021). "Recent evidence indicates that opioids can be active at a receptor that is abundantly expressed on innate immune cells as well as cancer cells: the receptor is termed toll-like receptor 4 (TLR4)." (PMID 34771442, 2021). "TGF-β secreted by TLR4-expressing cancer cells (in our case THP-1 human AML cells), displays autocrine/paracrine activities, and thus acts on the malignant cells which have produced it." (PMID 34234778, 2021).
cancer (continued). "Taken together, our results suggest that HMGB1 potentially plays a critical role in anti-cancer immune evasion and these effects are facilitated by TLR4." (PMID 34234778, 2021). "The results showed that the five TLR4 prognosis-related cancers KIRC, SKCM, STAD, TGCT, and UCEC were related to ICOS, CTLA4, CD28, and CD80." (PMID 34631699, 2021). "Recent studies have shown that TLR4 overexpression not only counteracts apoptosis, but also promotes proliferation, invasion, and metastasis in several cancer cells." (PMID 34502140, 2021). "There have been numerous studies on the promotive effects of TLR4 expression on the development and metastatic progression of different cancer types." (PMID 33576897, 2021). "Previous studies on these genes suggested that TLR4 is required for protective immune response and to kill cancer cells." (PMID 33777800, 2021). "On the contrary, TLR4 not only involves in innate immune system but also activates adaptive immune system in response to cancer." (PMID 34385421, 2021). "TLR4 activation leads to a strong pro-inflammatory response in macrophages; however, it is also recognised to play a key role in cancer." (PMID 34771442, 2021). "As the activator of TLR4, the existence of LPS has been widely confirmed in cancers from recent studies." (PMID 34718325, 2021). "Activation of TLR4 has been shown to enhance DC maturation which promoted anticolorectal cancer T cell response in vitro." (PMID 34124272, 2021). "A major endogenous TLR4 agonist, that is relevant to cancer, is the DAMP high-mobility group box 1 (HMGB1), which possesses protumour characteristics through sustaining an anti-inflammatory environment and promoting invasion metastasis and angiogenesis." (PMID 34771442, 2021). "For example, a change in the structure of lipid A to hexa-acylated lipid A, has led to increased affinity for Toll-like receptor 4 (TLR4), which can induce anti-cancer responses." (PMID 34960243, 2021). "Pei and colleagues demonstrated that PC3 human prostate epithelial cells constitutively express TLR4, which plays an important role in cancer development." (PMID 33919077, 2021). "More importantly, Toll-like Receptor 4 (TLR4) agonists always have an application in the field of cancer immunotherapy." (PMID 34149807, 2021). "Among the signaling cascades included in our reconstruction, we included the following interactions: Cancer dying cells produce HMGB1 activating Toll-like receptor 4 (TLR4), consequently activating NFκB." (PMID 34177892, 2021). "Comprehensive analysis of TLR4 expression is necessary; moreover, exploring effective prognostic biomarkers can help optimize the prognostic evaluation system of cancer." (PMID 34631699, 2021). "Observed higher levels of active p38β MAPK, NF-κB and AKT in the RA of cancer patients are consistent with TLR4 activation by elevated circulating Hsp70 and Hsp90." (PMID 34950660, 2021). "In view of the limited reports of TLR4 expression in different cancer types, it is challenging to reach any conclusion at present." (PMID 34631699, 2021). "Based on this evidence, to date, various therapeutic drugs for activating TLR4 in cancer treatment has been implemented." (PMID 34844644, 2021). "Reports state that TYROBP, TLR4, and ITGAM are involved in several cancer-immune microenvironment-associated pathogeneses, including OS23." (PMID 34588497, 2021). "Collectively, these studies suggest promotive roles for TLR4 in the development and metastasis of cancer." (PMID 33576897, 2021). "Toll-like receptor 4 (TLR4) is an important signaling pathway in inflammation which also plays a role in cancer prevention." (PMID 34844644, 2021). "Our data clearly demonstrate that TLR4 is a master regulator for CRC growth under HFD by programming cancer metabolism." (PMID 34385421, 2021). "TLR4 agonists have been tested as adjuvants in vaccines against infectious diseases, anti-allergic treatments and as immunotherapy against cancer." (PMID 33499143, 2021).